FSCN1 (fascin actin-bundling protein 1)
Diseases named in the same sentence as FSCN1 in open-access papers (continued):
Sharing a sentence is not in itself a finding about the gene and the disease.
cancer (continued). "While upregulated expression of FSCN1 was found to be correlated with enhanced cell proliferation in different cancer cell lines, few studies reported no significant cell proliferation in FSCN1-transduced cancer cells." (PMID 34830909, 2021). "The data identify novel roles for CREB and AhR as major, specific regulators of FSCN-1 transcription in human carcinoma cells but do not support the hypothesis that β-catenin signaling has a central role." (PMID 19340314, 2009). "In addition, other cellular physiological processes, such as extracellular vesicle release, focal adhesion dynamics, cancer cell stemness, histone methylation, and gene transcription are independent of the actin-bundling activity of FSCN1." (PMID 35401239, 2022).
infection (4 papers, 2016 to 2025). The state of being infected such as from the introduction of a foreign agent such as serum, vaccine, antigenic substance or organism. "For instance, the proteins FMNL3, EPB41L1, SSH2, CORO1B and ARPC2 are detected only in E. ruminantium-infected cells, while in FSCN1 and GC, proteins are under-expressed or inhibited by infection." (PMID 34073568, 2021).
retinopathy (1 paper, 2023). "Firstly, we re-analyzed publicly available scRNA-seq data (GEO: #GSE150703) of oxygen-induced retinopathy mice (OIR) and normoxic mice (NORM) to investigate the cellular localization of FSCN1 in the retina." (PMID 37596693, 2023).
FSCN1 also shares sentences with these, for which no sentence is quoted: nasopharyngeal carcinoma (5 papers); adenocarcinoma (3); glioblastoma (3); glioma (3); laryngeal carcinoma (2); pancreatic ductal adenocarcinoma (2); acute lymphoblastic leukemia (1); adrenal tumors (1); age-related macular degeneration (1); amelanotic melanoma (1); anaplastic large cell lymphoma (1); benign ovarian tumors (1); cardiovascular disease (1); cervical adenocarcinoma (1); classic Hodgkin lymphoma (1); clear cell carcinoma (1); clear cell renal cell carcinoma (1); co-infection (1); cocaine addiction (1); colitis (1); colorectal adenocarcinoma (1); cryptorchidism (1); cystadenoma (1); dry age related macular degeneration (1); ductal carcinoma in situ (1); experimental autoimmune encephalomyelitis (1); gastric adenocarcinoma (1); gastrointestinal disorder (1); gastrointestinal stromal tumor (1); head and neck squamous cell carcinoma (1).
A further 30 diseases each share a sentence with FSCN1 in 1 paper.